SNORD114-26 (small nucleolar RNA, C/D box 114-26)
Synonyms: 14q(II-26)
Gene: Small nucleolar RNA gene on chromosome 14 (100,987,046 to 100,987,117, forward strand). Ensembl gene ENSG00000200413.
Gene Ontology:
Biological process: RNA processing
Cellular component: nucleolus
Homologues: Orthologues: chimpanzee SNORD114-26 (100% identical), macaque SNORD114-26 (97% identical), rat Snord114-9 (67% identical). Paralogues in human: SNORD114-23 (92% identical), SNORD114-15 (90% identical), SNORD114-21 (90% identical), SNORD114-28 (90% identical), SNORD114-22 (89% identical), SNORD114-9 (89% identical), SNORD114-25 (88% identical), SNORD114-5 (88% identical), SNORD114-20 (86% identical), SNORD114-3 (86% identical), SNORD114-18 (83% identical), SNORD114-29 (83% identical), and 26 more.